CD163 (CD163 molecule)
Diseases named in the same sentence as CD163 in open-access papers (continued):
Sharing a sentence is not in itself a finding about the gene and the disease.
tumor (continued). "Taken together, high expression of M2-related cytokines in MPE-derived CD163+ macrophages demonstrates that CD163+ TAMs are defined as M2 macrophages in MPE, and closely associated with tumor progression." (PMID 25871392, 2015). "A more pronounced increase of tumor promoting CD163+ macrophages was observed in the aggressive AT-1 and MatLyLu tumors compared to the indolent G tumors and compared to controls." (PMID 26536349, 2015). "On treatment, tumor biopsies showed intense infiltration with CD8+ T cells and CD163+ dendritic macrophages within the tumor vasculature." (PMID 26442214, 2015). "Differences in the numbers of CD68+ and CD163+ macrophages in the tumor microenvironment of cHL have already been shown by others and by us." (PMID 25978381, 2015). "The cancer cells were considerable heterogeneous in the distribution of CD163 expression in different regions of the same section and in the same tumor specimen." (PMID 26585897, 2015). "The expression of CD68 (all macrophages, DCs, and neutrophils) tended to be higher than that of CD163 (pro-tumor macrophages)." (PMID 26374556, 2015). "The study also showed that IL-8 enhanced generation of CD163-positive M2 macrophages, and that CD163 positivity at the tumor invasion front correlated with significantly worse overall survival and disease-free survival in OSCC." (PMID 25999952, 2015). "Our results show that CD163 expression is associated with poor prognosis and correlates with VEGF expression and MVD, which suggests a role for TAMs in tumor angiogenesis." (PMID 24489836, 2014). "At low numbers, CD68+ (H1) and CD163+ (I1) macrophage predominantly localized close to tumor cells while at higher numbers, both macrophage populations were equally distributed throughout the tissues, respectively (H2,I2)." (PMID 24797069, 2014). "We demonstrated that tumor cells, in addition to inducing CD163 expression in macrophages, are capable of influencing the profile of cytokine secretion by means of these cells." (PMID 25309919, 2014). "vi) A tumor-related localization of CD68+ (H2) and CD163+ (I2) macrophages was associated with a high abundance of myofibroblasts (L2)." (PMID 24797069, 2014). "We examined the expression of IL-8 in tumor cells (IL-8(T)) and CD163-positive cell-infiltration into the tumor invasive front (CD163(IF)) by immunohistochemical staining." (PMID 25461761, 2014). "CD8 positive T-cells and the total macrophage count, using the CD68 pan-macrophage marker, and CD163 positive M2 macrophage count were determined in tumor specimens prior to treatment." (PMID 25192022, 2014). "Surprisingly, in GBMs treated with oncolytic viruses, both phagocytic marker CD68 and tumor suppressive macrophage marker CD163 were elevated in subpopulations of TAMs." (PMID 24675569, 2014). "viii) A high abundance of fibroblasts (L1) in the tumoral stroma correlated with increased L1CAM expression in the carcinoma cells (P2) and high numbers of CD68+ (H1) and CD163+ (I1) macrophages correlated with elevated vimentin expression in tumor cells (R)." (PMID 24797069, 2014). "Results showed that most tumor tissues had higher densities of CD163+ and CD68+ macrophages infiltration than those in the tumor-free tissues." (PMID 25144454, 2014). "We also studied the expression of CD163 on tumor cells, but found few CD163-expressing tumor cells in HCC." (PMID 23555776, 2013). "In this aspect, MDSCs in human are translated CD163+, ARG1+, and alternatively activated, tumor-associated macrophages (TAM)." (PMID 23606867, 2013). "In this study, the distribution and clinical significance of macrophages in tumor and peritumoral liver tissues were evaluated with the markers of CD163 and CD68, and the differences between these two markers were analyzed." (PMID 23555776, 2013). "We therefore evaluated the number of CD68 and CD163 positive macrophages in the tumor microenvironment using IHC analysis." (PMID 24236041, 2013).
tumor (continued). "Immunostaining on consecutive sections of tumor tissue and peritumoral liver tissue also showed that the density of CD163+ cells was much higher than that of the CD68+ cells both in tumor and in peritumoral liver tissue." (PMID 23555776, 2013). "The densities of CD68+ and CD163+ cells in peritumoral liver tissue were significantly higher than those within tumor (P<0.001 for both)." (PMID 23555776, 2013). "In cohort 1, the density of CD163+ cells was positively correlated with that of CD68+ cells in tumor tissue (r = 0.417, P<0.001) and peritumoral liver tissue (r = 0.565, P<0.001)." (PMID 23555776, 2013). "In mice bearing sub-cutaneous EL4 tumors, which are CD115-negative, the anti-CD115 mAb depleted F4/80+ CD163+ M2-type TAMs and reduced tumor growth, resulting in prolonged survival." (PMID 24019914, 2013). "CD68 and CD163 staining appeared mainly in the cytoplasm of stroma cells in tumor and peritumoral liver tissue." (PMID 23555776, 2013). "In fact, CD163+ “tumor-promoting” M2 macrophages which can be abundant in the microenvironment of colorectal carcinomas are activated by cetuximab and in turn they release anti-inflammatory and tumor-promoting mediators, including IL-10 and VEGF." (PMID 23316197, 2012). "Expression of NOS2 and CD163 inversely correlated to tumor stage, indicating that higher stage tumors to a larger extent have escaped the immune system." (PMID 23077543, 2012). "NOS2 and CD163 expression at the tumor invasive front in relation to clinicopathologic characteristics in CRC." (PMID 23077543, 2012). "Because of the strong correlation between tumor stage and the expression of NOS2 and CD163 we performed multivariate Cox proportional hazard models including the variables gender, age, localization, tumor stage, and one macrophage marker, respectively." (PMID 23077543, 2012). "The majority of NOS2 and CD163 expression was found in cells located in the tumor stroma, with the highest density along the invasive tumor front." (PMID 23077543, 2012). "In our study, dense infiltration of CD163+ macrophages located in TS correlated with grade, tumor size, subtypes and receptor status." (PMID 22824040, 2012). "Accordingly, CD3 and CD163 specific staining data indicate that tumor infiltration by FOXP3+ cells is highly correlated with infiltration by CD3+ cells." (PMID 22471961, 2012). "We observed a higher tumor infiltration by CD3 positive cells (average: 37.9 per punch) than by CD163 positive cells (average: 21.6 per punch)." (PMID 22471961, 2012). "A strong inverse association with tumor stage was found for both NOS2+ (P<0.0001) and CD163+ (P<0.0001) macrophage infiltration." (PMID 23077543, 2012). "The average infiltration of NOS2 and CD163 expressing macrophages along the invasive tumor front was semi-quantitatively evaluated using a four-graded scale." (PMID 23077543, 2012). "According to subject literature, CD163 is expressed not only by normal monocytes/macrophages but also by neoplasms." (PMID 22353646, 2012). "The amounts of CD163+ cells at the tumor front, however, were frequently higher than that of NOS2+ cells." (PMID 23077543, 2012). "NOS2 and CD163 expression at the tumor invasive front in relation to molecular characteristics in CRC." (PMID 23077543, 2012). "Infiltrating CD163 positive macrophages were found in the tumor stroma, and the levels were significantly higher than in the control group (P < 0.001)." (PMID 22190968, 2011). "CD163+ cells were detected in the tumor stroma in grade I tumors, whereas an increase in the CD163+ cells in the tumor nest was observed in higher grades of tumors." (PMID 24213108, 2011). "Immunohistochemical staining in the tumor cells was positive for CD163, CD68, lysozyme, CD45, and NSE." (PMID 17324277, 2007). "All specimens contained cells positive for CD68, CD163, S100 and CD1a in epithelial tumor tissue and tumor stroma." (PMID 18047662, 2007).
tumor (continued). "While CD68+ macrophages were neither increased nor decreased in limited or advanced stages, both S100 DC and CD163 macrophages were increased in the tumor stroma in limited disease (UICC I +II) compared to advanced disease (UICC III + IV)." (PMID 18047662, 2007). "CD163+ M2 macrophages can aid in the immunological escape of tumor cells and increase tumor growth." (PMID 41583517, 2026). "Clinical cohort studies have also demonstrated that increased total TAM density in NSCLC tissues and elevated ratios of the M2 marker CD163 to the pan‐macrophage marker CD68 (i.e., CD163/CD68 ratio) are associated with advanced tumor stage, higher metastatic risk, and poor prognosis." (PMID 41426206, 2026). "However, high RDH16 expression in normal liver tissue correlates with CD3+ lymphocyte infiltration, while its absence in tumor regions negatively correlates with CD163+ histiocytic infiltration." (PMID 41601632, 2026). "Notably, RDH16 expression was inversely correlated with infiltration of CD163+ M2 macrophages, suggesting a potential immunomodulatory role in the tumor microenvironment." (PMID 41601632, 2026). "Additionally, macrophage density was higher in tumors with ulceration, and both CD68+ and CD163+ macrophage numbers increased progressively with tumor stage, particularly in advanced stages." (PMID 41007741, 2025). "Immunohistochemical analysis further confirmed that Gel/G4-Arg/DOX treatment was associated with reduced expression of the M2 macrophage marker CD163 and increased expression of the M1 marker CD11c, indicating a favorable shift in the ratio of anti-tumor to pro-tumor macrophage phenotypes." (PMID 41294574, 2025). "When co-cultured with THP-1 macrophages, OCSLCs increase the expression of M2 markers such as CD163, while boosting the secretion of anti-inflammatory cytokines like IL-10 and pro-tumor factors such as VEGF and MMP-9, which are characteristic of M2 macrophages." (PMID 40330466, 2025). "However, we found statistical relevance for DFS for CD68+CD163+MPO+ cells in the epithelial compartment of tumor distant normal tissue." (PMID 40498004, 2025). "Furthermore, tissue immunofluorescence staining underscored the treatment’s efficacy in upregulating the M1 macrophage marker CD86 and downregulating the M2 macrophage marker CD163 within the tumor milieu." (PMID 40664640, 2025). "A previous study of the TME in IBC showed that lower pretreatment mast cell density was significantly associated with achieving pCR and that mast cells in proximity to CD163 + monocytes/macrophages and tumor cells was associated with not achieving pCR." (PMID 41024110, 2025). "This could be attributed to the suppression of the TIL response and the promotion of tumor angiogenesis by CD163+ M2 macrophages." (PMID 40141426, 2025). "Moreover, CD163 involvement extends beyond cytokine production, as it influences macrophage–tumor cell interactions, facilitating tumor cell adaptation and proliferation, especially during early tumor development." (PMID 40423041, 2025). "In contrast, CD163 can show extensive extracellular deposition within necrotic tumor areas." (PMID 40361384, 2025). "PD-L1 expression correlated with CD163-positive macrophage infiltration, suggesting that M2-TAMs may promote PD-L1 expression in human GC tumor cells." (PMID 41142606, 2025). "Furthermore, in another study, CD163, acting as a macrophage marker, was found to play a significant role in regulating inflammation and the tumor microenvironment." (PMID 40630963, 2025). "Notably, BCL2A1+macrophages exhibited significant differences from CD163+macrophages within tumor tissues." (PMID 40707992, 2025). "Furthermore, we confirmed the presence of CD86+ (M1) and CD163+ (M2) macrophages in the tumor microenvironment by using immunofluorescence analysis on frozen tumor sections derived from SeAx/MyLa cell xenografts in the CAM of chicken embryos." (PMID 41221277, 2025).
tumor (continued). "We observed CD163+ M2 TAMs only at the primary tumour periphery, with minimal infiltration into the tumour, suggesting that the CD68+ cells within the OS tumours were non-M2 myeloid lineage cell types, such as M1 TAM or osteoclasts, while M2 TAM congregate at the tumour invasive edge." (PMID 41315643, 2025). "In addition, experiments in mice models have suggested the important role of CD163+ macrophages in tumor growth and metastasis." (PMID 40425576, 2025). "Ablation of sympathetic nerves, on the other hand, leads to increased tumor growth and spread, suggesting that CD163+ macrophages may mediate the pro-tumor effects of sympathetic nerve resection." (PMID 40149585, 2025). "A suggestive inverse correlation was detected between CD8 T cells and CD163 + M2 macrophages, suggesting that the abundance of TAMs might predict the scarcity of tumor-infiltrating T cells." (PMID 40179060, 2025). "Indeed, the present in vivo results demonstrated a large number of CD163 positive cells in tumor tissues of co-xenografts mice." (PMID 40332513, 2025). "In our earlier study, we tested whether quantifying CD8+ and CD163+ cells, individually and in combination, in both the tumor center (TC) and the invasive margin (IM) could refine immunoscoring in BCa and enhance conventional prognostic indicators." (PMID 41374956, 2025). "Similarly, elevated infiltration by CD163+ M2 macrophages has been correlated with increased tumor aggressiveness and reduced progression-free survival, particularly in advanced and castration-resistant cases." (PMID 41179298, 2025). "However, it reduced the expression of CD163 antigens in tumor areas, indicating increased macrophage infiltration into the tumor area and differentiation into the M1 subtype of macrophages." (PMID 41455906, 2025). "Interestingly, we found that TLR9 expression was colocalized with CD163+ macrophages in tumor tissues from HCC patients." (PMID 40038250, 2025). "The regulation of CD163 is crucial for M2 macrophage polarization, while the other immunosuppressive genes contribute to the establishment and reinforcement of an immunosuppressive tumor microenvironment." (PMID 40539245, 2025). "In contrast, necrotic tumor areas were typically strongly and diffusely CD163 positive." (PMID 40191733, 2025). "In addition to the quantitative increase in CD163+ TAMs at the pT2 stage, a notable feature was their tendency to concentrate more densely in the central region of the tumor, as clearly illustrated by the density map." (PMID 40843751, 2025). "CD16, CD64, and CD163 are markers of NK cells and TAMs in the tumor microenvironment, respectively." (PMID 41181127, 2025). "We and others have demonstrated that CD163+ M2-like tumor-associated macrophages (TAMs) affect the prognosis of HNSCC, but the roles played by CD163– TAMs in antitumor responses remain unclear." (PMID 40025278, 2025). "However, pT2 tumors showed a trend toward higher CD163+ TAMs density, suggesting increased M2 polarization with advancing tumor stage." (PMID 40843751, 2025). "Inside the tumor parenchyma, the CD163+PD-L1+ cells were the most densely populated subset." (PMID 40422521, 2025). "Clinically, TAM-targeted therapies could complement existing treatments, with biomarkers like CD163 and IL-10 guiding personalized interventions, ultimately improving tumor control and patient outcomes through optimized multimodal strategies." (PMID 40264780, 2025). "BCL2A1+macrophages may influence tumor progression through apoptosis regulation and modulation of immune responses, whereas CD163+macrophages may be involved in antigen presentation." (PMID 40707992, 2025).
tumor (continued). "The higher expression of FOXP3 and CD163, specifically in the hematologic metastasis, suggests a more immunosuppressive tumor microenvironment at this stage of the disease, possibly reflecting greater infiltration of Tregs and M2-type macrophages, respectively." (PMID 41179298, 2025). "The main objective of this study was to investigate the relationship between the expression levels of Trop-2, CD47, and CD163, as assessed by immunohistochemistry in tumor tissue, and clinical outcomes and survival in TNBC, which is characterized by an aggressive clinical course and poor prognosis." (PMID 39857116, 2025). "CD163+ M2 macrophages also correlate with tumor progression." (PMID 41267985, 2025). "Functionally, CD163+ TAMs foster tumor immune evasion; their depletion in melanoma models increases cytotoxic T cell infiltration and inflammatory monocyte recruitment, markedly enhancing tumor regression." (PMID 40948759, 2025). "Notably, CD163+ macrophages showed a pronounced relative increase, especially in the peritumoral stroma, suggesting their significant role in tumor microenvironment remodeling." (PMID 41007741, 2025). "Similarly, melanomas with dense CD163+ cell infiltration in the tumor stroma, and CD68+ infiltration at the tumor front were associated with poorer OS." (PMID 39825956, 2025). "CXCL13+ CD8+ T cells interacted with SPP1+ tumor-associated macrophages (TAMs) in non-recurrent tumors, while in recurrent tumors, they interacted with CD163+ TAMs." (PMID 40464813, 2025). "To assess M2 polarized TAMs, we used IHC to detect CD163+ in the primary tumour." (PMID 41315643, 2025). "To explain the discrepancy, we suggest that tumor secretions could modify the microenvironment at distant sites, increasing CD163+ microglia in apparently normal samples devoid of cancer cells." (PMID 40703808, 2025). "Tumor macrophages demonstrated significant upregulation of genes associated with polarization to the tumorigenic and immunosuppressive M2 phenotype (e.g., APOE, CD163, WNT5A, and THBS1)." (PMID 40848148, 2025). "The increased tumor growth in MISTRG-6 mice may be due to the high number of tumor-infiltrating CD163+ human macrophages." (PMID 40503011, 2025). "Interestingly, CD163-positive cells were highly enriched in the proximal region from the tumor compared with distal regions, indicative of an increased number of TAMs more closely located near the tumor lesions." (PMID 40526430, 2025). "Furthermore, the regressing tumor exhibited a rise in both CD163:CD68 and FoxP3:CD4 ratios, suggesting that the inflammation driving STR was associated with an upregulation in immunosuppressive M2 macrophages and regulatory T-cells (Tregs), respectively." (PMID 40594889, 2025). "Additionally, flow cytometry analysis of syngeneic tumor samples revealed that exogenous succinate partially reversed the decrease in F4/80+CD11b+CD206+ and F4/80+CD11b+CD163+ macrophages proportion caused by INHBA knockdown." (PMID 41449244, 2025). "However, the dynamics of different macrophage subsets, particularly CD68+ and CD163+ populations, in relation to tumor thickness and stage remain insufficiently characterized." (PMID 41007741, 2025). "Although with controversy, it has been reported that CD68+ cells and CD163+ M2-like macrophages may have relevance with tumor progression and poor prognosis." (PMID 40539047, 2025). "As expected, the overall number of CD68+CD163− M1-type macrophages were rather low, with 0.9 cells/mm2 tumor near and 1.4 cells/mm2 tumor distant in the stromal compartment and 8.1 cells/mm2 and 6.0 cells/mm2 in the epithelial compartment of samples of the APBI studies." (PMID 40498004, 2025). "Tumor co-culture induced further enhancement of M1-associated markers including CD80/CD86, MHC-II and IL-1β/IL-6/TNF-α/IL-12/IFN-γ, while suppressing M2 markers CD163/CD206, indicating tumor-triggered M1 polarization." (PMID 41388305, 2025).